CD1C (CD1c molecule)
Diseases named in the same sentence as CD1C in open-access papers (continued):
Sharing a sentence is not in itself a finding about the gene and the disease.
malaria (7 papers, 2016 to 2025). Malaria is a serious and sometimes fatal disease caused by a parasite that commonly infects a certain type of mosquito which feeds on humans. "Consistently these cytokines were negatively associated with B cell subsets expressing CD1c, which increased frequencies were linked to malaria exposure." (PMID 40321757, 2025). "CD1c expression in dendritic cells has been positively associated to Pf-malaria exposure and protection." (PMID 40321757, 2025). "During clinical malaria, plasmacytoid DCs (pDCs), CD1c+ DCs (BDCA1, DC2) and CD141+ DCs (BDCA3, DC1) numbers significantly decreased in both P. falciparum and P. knowlesi infection when compared to healthy uninfected controls." (PMID 33593383, 2021). "In contrast, during both experimental subpatent infection and clinical malaria, HLA‐DR expression is reduced on classical CD1c+ DC,50, 51 which are typically considered superior antigen‐presenting cells." (PMID 32566226, 2020). "In summary, cumulative but not a single (vaccine) malaria exposure was associated with increased frequencies of many B cell subsets, with higher and lower percentages of CD1c and IgG expressing-cells respectively." (PMID 40321757, 2025). "In conclusion, lifelong but not vaccine exposure to malaria was associated with increased frequencies of multiple B cell subsets, with higher and lower percentages of CD1c and IgG expressing-cells, respectively." (PMID 40321757, 2025). "Plasma Flt3L concentration and blood CD141+ DC, CD1c+ DC and plasmacytoid DC (pDC) numbers were assessed in (i) volunteers experimentally infected with P. falciparum and in Malaysian patients with uncomplicated (ii) P. falciparum or (iii) P. knowlesi malaria." (PMID 33593383, 2021). "Interestingly, baseline frequencies of CD1c+ cells within each B cell subset, were higher in the semi-immune compared to naïve individuals, correlated negatively with eotaxin and positively with anti-Pf antibodies, the latter well-known markers of malaria exposure." (PMID 40321757, 2025). "In contrast, as previously reported, pDC and CD1c+ mDC numbers were significantly reduced and CD141+ mDC were unchanged in adults with acute uncomplicated malaria." (PMID 27328659, 2016). "Similarly, this study shows that pDC, CD1c+ DC and CD141+ DCs subsets are significantly reduced during clinical falciparum and for the first time, also in knowlesi malaria." (PMID 33593383, 2021). "Furthermore, the previously reported loss of pDC, CD1c+ DC and CD141+ DC subsets was confirmed in adults with acute falciparum malaria; and for the first time a significant decline in pDC, CD1c+ DC and CD141+ DC subsets in acute uncomplicated knowlesi malaria is reported." (PMID 33593383, 2021).
autoimmune disease (6 papers, 2014 to 2025). A disorder resulting from loss of function or tissue destruction of an organ or multiple organs, arising from humoral or cellular immune responses of the individual to their own tissue constituents. "In the present study, we describe for the first time to our knowledge that SF CD1c+ cDC from patients with RA preferentially display a high capability to activate pathogenic IL-17+IFN-γ+CD4+ T cells involved in autoimmune diseases." (PMID 36194479, 2022). "CD1c reactive T cells have been detected at high frequency in human blood expand during tuberculosis infection and might have a pathogenic role in autoimmune disease, and CD1c expression is modulated by inflammatory cytokines." (PMID 40777002, 2025). "In this respect, increased numbers of CD14-expressing monocytes, CD68 or CD163-expressing macrophages, CD1c or CD11c-expressing myeloid dendritic cells have been documented in different autoimmune diseases." (PMID 24740301, 2014). "CX3CR1 levels were also not significantly different in sorted CD5−CD163+CD14-positive and CD14-negative DC3s from patients with autoimmune diseases, further indicating that CX3CR1 expression in CD1c+ DCs may be independent from CD14 expression in CD1c+ DCs." (PMID 37042831, 2023).
lung adenocarcinoma (6 papers, 2016 to 2024). A carcinoma that arises from the lung and is characterized by the presence of malignant glandular epithelial cells. "CD1c+ DCs can be generated at the tumor site; their elevated numbers were noted in lung adenocarcinoma tumors as compared with normal lung tissue." (PMID 35955602, 2022). "After dendritic cells infiltrated into lung adenocarcinoma and were educated via interaction with various cells including cancer cells in the tumor microenvironment, they were differentiated into CD1c− and CD1c+ subpopulations." (PMID 32434423, 2020). "A study on early lung adenocarcinoma with EGFR mutation found that the infiltrating T cell types were mainly exhausted and regulatory T cells, which were associated with an increase in dendritic cells expressing the CD1c gene precisely." (PMID 38099311, 2023). "Comparison of transcriptomes of CD1c negative (CD1c−) and positive (CD1c+) dendritic cells which infiltrated into lung adenocarcinoma with those located at juxtatumor indicated that there were 2846 and 1313 genes that had more than 1.5-fold increase in expression, respectively." (PMID 32434423, 2020).
metastatic melanoma (6 papers, 2019 to 2024). A melanoma that has spread from its primary site to another anatomic site. "Herewith, we add enrichment of CD1c+CD14+ myeloid cells in NSCLC patients to the previous observations in peripheral blood of metastatic melanoma and several tumor tissues." (PMID 38242119, 2024). "One of the few clinical studies to have exploited primary CD1c+ mDCs used them for the treatment of metastatic melanoma." (PMID 34122417, 2021).
lung carcinoma (5 papers, 2016 to 2024). "In contrast to previous studies, we found that the capacity of CD1c+ DCs to phagocytose necrotic lung cancer cells is similar to that of monocytes but stronger than that of other DCs." (PMID 32655564, 2020). "In our study, BDCA3+ (CD141+) DCs, CD1c+ DCs, and pDCs could cross-present antigens from necrotic lung cancer debris, and TLR agonists could further enhance this process." (PMID 32655564, 2020). "In scRNA-seq studies of lung cancer, CD141+ DCs clusters were revealed with marker genes of CLEC9A, XCR1, CD207, IRF8, and CD1C+ DCs clusters highly expressed CD1C, CX3CR1, FCER1A, and IRF4." (PMID 37187731, 2023). "According to our research, BDCA3+ (CD141+) DCs exhibit the strongest cross-presentation ability, followed by CD1c+ DCs, while CD16+ DCs and MoDCs cannot present antigens derived from necrotic lung cancer cells." (PMID 32655564, 2020). "Both CD141+ DCs and CD1C+ DCs in tumors have the potential to differentiate into LAMP3+ DCs upon uptake of tumor antigens, although more CD141+ DC-derived LAMP3+ DCs have been observed in lung cancer." (PMID 37187731, 2023).
ovarian carcinoma (5 papers, 2017 to 2025). A malignant neoplasm originating from the surface ovarian epithelium. "Related, a recent study investigating peritoneal MØ/DC subsets within tumor ascites from patients with advanced ovarian cancer also identified CD14+ MØs and CD1c+ DCs, through a different flow-cytometric gating approach." (PMID 28065517, 2017).
Arthritis (4 papers, 2017 to 2025). Inflammation of a joint. "Overall, our study provides important insights into DC3 development in arthritis and emphasises the importance of examining the individual CD1c+ DC subsets to understand their relative contribution to pathogenic processes." (PMID 40687784, 2025). "The presence of CD1c+CD14+CD163+ DC3s in SF from patients with arthritis aligns with the reports of CD163+ DC3s detected in SF and tissue in OA, and CD1c+CD14+ DCs described in inflammatory tumor ascites and RA SF." (PMID 40687784, 2025). "This emphasizes early involvement of these DC subsets in disease pathogenesis in keeping with previous observations in animal arthritis models where lymphatic CD1c+ DCs are important in breaching tolerance." (PMID 29867920, 2018). "All data considered, differences in detected CD1c+CD14+ DC3s frequencies might be related to the type of arthritis, onset of disease, and disease activity." (PMID 40687784, 2025). "We found a negative-feedback control of DC activation, mediated by miR-34a governing immunosuppressive AXL pathway activation, that is aberrant in circulating, SF and synovial tissue CD1c+ DCs of RA patients; and that also contributes to experimental arthritis." (PMID 28639625, 2017).
asthma (4 papers, 2014 to 2022). "The CD1C, TLR7, PTK2, CD1E, CD1A, and ERBB2 genes had a higher rate of engaging protein interactions in the PPI for the moderate-to-severe asthma phenotype." (PMID 32512817, 2020). "Similar to COPD and asthma, DCs accumulate in the lungs of patients with IPF and sarcoidosis, in particular CD1c+ MDCs." (PMID 28507549, 2017). "Although human MNPs have not been investigated in contributing to Th17-mediated asthma, existing studies suggest that CD1c+ MDCs can control mucosal IL-17 responses." (PMID 28507549, 2017).
gastric cancer (4 papers, 2021 to 2023). A primary or metastatic malignant neoplasm involving the stomach. "A previous study has shown that the counts of CD1C+ DCs in the blood of gastric cancer patients were increased." (PMID 36755259, 2023). "The count of CD1c+ DCs in the blood of gastric cancer patients increases." (PMID 38099311, 2023). "For example, the M1 Macrophage marker NOS2 and the dendritic cell marker, HLA-DPB1 and CD1C, were significantly correlated with ARHGAP11A expression in gastric cancer." (PMID 34733886, 2021).
non-small cell lung carcinoma (4 papers, 2019 to 2023). A group of at least three distinct histological types of lung cancer, including non-small cell squamous cell carcinoma, adenocarcinoma, and large cell carcinoma. "In non-small cell lung cancer, higher numbers of myeloid CD1c+ cells in tumor tissue were related to worse survival." (PMID 35955602, 2022). "This may be due to the up-regulation of the function of dendritic cells by Cd1c in TME of patients with non-small cell lung cancer." (PMID 34805160, 2021). "In non-small cell lung cancer (NSCLS), CD1C plays an antitumor role in vivo." (PMID 36755259, 2023).
Obesity (4 papers, 2011 to 2024). Accumulation of substantial excess body fat. "In human adipose tissue, CD1c, a dendritic cell marker, has been positively associated with insulin resistance, and murine CD11c+CD64- dendritic cells are specifically cited as independent contributors to obesity and insulin resistance in diet-induced obesity models." (PMID 39493777, 2024).
Sepsis (4 papers, 2020 to 2022). Sepsis is defined as life-threatening organ dysfunction caused by a dysregulated host response to infection. "CD1c+ DCs from sepsis patients expressed lower levels of CD86 and HLA-DR during early stage of the disease and remained at significantly lower levels at the later stage compared to their counterparts in the healthy donors." (PMID 34566996, 2021). "There was approximately an 8- to 10-fold reduction in both the frequency and number of CD1c+DCs and pDCs out of the total leukocytes of sepsis patients compared to that of the healthy donors." (PMID 34566996, 2021). "From days 3 to 7 of sepsis, the frequency of late apoptotic cells among the CD1c+ DCs and pDCs was approximately 4-fold and 7-fold greater than that of healthy donors." (PMID 34566996, 2021). "Therefore, sepsis also impairs DC maturation and activation, affecting CD1c+ cDCs to a greater extent." (PMID 34566996, 2021). "We found that approximately 2% of CD1c+DCs and 5.5% of pDCs from sepsis patients at days 1 to 3 of diagnosis were late apoptotic cells, whereas healthy donors had approximately 6-fold and 3-fold fewer late apoptotic cells among the CD1c+ DC (0.3%) and pDC (1.4%) subsets, respectively." (PMID 34566996, 2021). "It is likely that CD1c+ DCs are more sensitive than pDCs for predicting the severity of sepsis." (PMID 34566996, 2021).
acute leukemia (3 papers, 2014 to 2021). A clonal (malignant) hematopoietic disorder with an acute onset, affecting the bone marrow and the peripheral blood. "Collectively, these results highlight the efficacy of immunotherapy combining ACT plus tumor antigen-specific vaccination and confirmed the strong potential of a donor-unrestricted ACT approach for acute leukemia with CD1c-retargeted T cells." (PMID 34381053, 2021). "We show that transduction with the selected lead mLPA-specific TCR efficiently retargeted polyclonal T cells from a range of donors against CD1c-expressing acute leukemia cells in vitro, while sparing healthy CD1c-expressing circulating monocytes, Dendritic Cells (DC) and B cells." (PMID 34381053, 2021). "Having established that CD1c was abundantly expressed in acute leukemias and DLBCL, the next step was to identify the optimal CD1c-restricted TCR to retarget T cells against these malignancies." (PMID 34381053, 2021).
allergic reaction (3 papers, 2016 to 2024). "Thus, the decrease in Dectin-1 on CD1c+ DCs shown in the current study could have a beneficial or a disadvantageous effect on the allergic reaction." (PMID 26863539, 2016). "TSLP can stimulate the activation of primary human CD1c+ dendritic cells with the increased secretion of CCL17, a chemokine which is involved in many allergy and inflammation reactions." (PMID 39726595, 2024).
chronic obstructive pulmonary disease (3 papers, 2014 to 2019). A chronic and progressive lung disorder characterized by the loss of elasticity of the bronchial tree and the air sacs, destruction of the air sacs wall, thickening of the bronchial wall, and mucous accumulation in the bronchial tree. "The frequency of the CD1c+ subset (including the CD1c+CD14+ fraction) was increased in patients with chronic obstructive pulmonary disease, suggesting that these cells may be involved in the enhanced susceptibility of these patients to infections." (PMID 29250057, 2017).
hepatocellular carcinoma (3 papers, 2022 to 2025). A malignant tumor that arises from hepatocytes. "On the other hand, hepatocellular cancer (HCC) patient blood CD1c+ cells were identified as myeloid, IL-12 producing DCs, less abundantly represented in circulation of HCC patients than in healthy controls." (PMID 35955602, 2022). "In hepatocellular carcinoma (HCC), the elevation of the ILT4+CD1c+ subset in tumor tissue may play an essential role in immune suppression." (PMID 38099311, 2023).
Immunodeficiency (3 papers, 2015 to 2024). Failure of the immune system to protect the body adequately from infection, due to the absence or insufficiency of some component process or substance. "The CD1c Molecule (CD1C) gene encodes a protein presenting Class I MHC antigens to T cells, crucial in immune disorders." (PMID 38893126, 2024). "A mono-allelic T80A mutation of IRF8 was associated with a milder AD immunodeficiency and a partial reduction of CD11c+/CD1c+ circulating DCs, which led to BCGosis without other infectious diseases." (PMID 36569938, 2022). "In conclusion, our data demonstrate that CD1c+ and CD16+ mDCs are differently modulated during SIV infection and might play different roles in SIV-associated immunodeficiency." (PMID 25915601, 2015).
influenza (3 papers, 2014 to 2022). An acute viral infection of the respiratory tract, occurring in isolated cases, in epidemics, or in pandemics; it is caused by serologically different strains of viruses (influenzaviruses) designated A, B, and C, has a 3-day incubation period, and usually lasts for 3 to 10 days. "We observed polarization of CD1c+ DC response to Gardasil (HPV), IL-4 DCs response to Fluzone (influenza) and monocyte response to Pneumovax (pneumococcus), suggesting that responses to different vaccines may be mediated through unique APC subsets." (PMID 25335753, 2014).
Insulin resistance (3 papers, 2019 to 2024). Increased resistance towards insulin, that is, diminished effectiveness of insulin in reducing blood glucose levels. "- Higher abundance of CD11c+/CD1c+ DCs in subcutaneous fat correlates with insulin resistance in morbidly obese patients." (PMID 35574032, 2022).
prostate carcinoma (3 papers, 2015 to 2020). A carcinoma that arises from epithelial cells of the prostate gland. "Previously, Prue and colleagues performed a phase I trial with HLA-A*0201 peptide-loaded CD1c+ DCs in 12 prostate cancer patients." (PMID 31727154, 2019). "Clinical studies utilizing protamine-mRNA matured pDCs and CD1c+ mDCs are currently ongoing in patients with prostate cancer and melanoma." (PMID 28536413, 2015).
psoriatic arthritis (3 papers, 2016 to 2021). Joint inflammation associated with psoriasis. "We found that, in contrast to healthy PB CD4+ T cells, psoriatic arthritis and in particular RA-SF CD4+ T cells supported the development of a population of CD1c+ DCs." (PMID 25923217, 2016).
renal cell carcinoma (3 papers, 2022 to 2023). "In renal cell carcinoma, patients with a high expression of CD1C had a better immunotherapy effect." (PMID 36755259, 2023). "In renal cell carcinoma, CD1c+ DCs predict progression-free survival." (PMID 38099311, 2023). "The frequency of CD1c+ dendritic cells could predict the progression-free survival of renal cell cancer patients." (PMID 36569825, 2022).
tuberculosis (3 papers, 2012 to 2025). A chronic, recurrent infection caused by the bacterium Mycobacterium tuberculosis. "These immediately implicate a unique role for CD1c in lipid antigen presentation and host defense against tuberculosis." (PMID 22536277, 2012). "Using the MPP compound with a C35 alkyl chain as a reference antigen, they detected the circulating CD1c-restricted, antigen-specific T cells in active tuberculosis patients, but not in healthy individuals." (PMID 22536277, 2012).
uveitis (3 papers, 2018 to 2025). An inflammatory process affecting a part of or the entire uvea. "Other disease modifying factors possibly affect the CD1c+ DC pool in uveitis patients." (PMID 37042831, 2023). "We constructed co-expression networks that identified a robust gene module associated with non-infectious uveitis in patients that helped identify a CX3CR1-positive CD1c+ DC subset." (PMID 37042831, 2023). "A CX3CR1 gene module in CD1c+ dendritic cells (CD1c+ DC) is associated with non-infectious uveitis." (PMID 37042831, 2023). "(G) Manual gating strategy of CD1c+ DC subsets based on CD36 and CX3CR1 in PBMCs in uveitis cases and controls." (PMID 37042831, 2023). "Single-cell analysis supported that CD1c+ DCs in eye fluid of patients with non-infectious uveitis contain also a population that has a gene profile reminiscent of CX3CR1+ DC3s, with relatively higher levels of CX3CR1, CD36, CCR2, and lower levels of RUNX3." (PMID 37042831, 2023). "It is tempting to speculate that the enrichment for NOTCH gene signatures implies altered NF-κB-Relb signaling in CD1c+ DCs, with a mechanism that varies between diseases mediated by type I IFNs (e.g., SLE) and type I IFN-negative diseases (e.g., uveitis)." (PMID 37042831, 2023). "We analyzed CD1c+ DCs from two cohorts of non-infectious uveitis patients and healthy donors using RNA-sequencing followed by high-dimensional flow cytometry to characterize the CD1c+ DC populations." (PMID 37042831, 2023). "We confirmed a decrease in the proportion of circulating plasmacytoid (p)DCs in human non-infectious uveitis, but were unable to ascertain a significant increase in CD1c-positive myeloid DCs (mDC1)." (PMID 30429855, 2018). "Perhaps targeting CD1c+ DCs may be achieved by dietary (microbiome) strategies and provide relatively safe preventive strategies for non-infectious uveitis." (PMID 37042831, 2023). "The differences between non-infectious uveitis and SLE may be related to distinct (i.e., opposite) immunopathological mechanisms; Type I IFNs drive the maturation of cDC2s into ‘inflammatory cDC2s’ (infcDC2s) and can induce CD1c+ DCs to express a distinct set of surface receptors." (PMID 37042831, 2023).